GCG (glucagon)
Diseases named in the same sentence as GCG in open-access papers (continued):
Sharing a sentence is not in itself a finding about the gene and the disease.
anaphylaxis (9 papers, 2014 to 2023). An acute hypersensitivity reaction that occurs from exposure to an allergen. "Andjelkovic and Zlokovic came into conclusion, a long time ago, that glucagon pretreatment decreased histamine release during anaphylaxis and thus caused beneficial effects in the heart during cardiac anaphylaxis." (PMID 24895609, 2014). "Namely, decrease of BF in the presence of glucagon indicates that glucagon intensifies histamine capturing even before anaphylaxis, potentially by activating the mechanisms underlying the cellular histamine uptake leading to the clearance of histamine in the local histamine-enriched environment." (PMID 24895609, 2014). "Though this is a less common side effect of the drug, more scientific data are required on the use of glucagon in hypertensive anaphylaxis." (PMID 36008817, 2022). "Some relevant examples include the delivery of adrenaline for the treatment of anaphylaxis or glucagon for the treatment of hypoglycaemic coma." (PMID 35922421, 2022). "International guidelines and consensus recommended glucagon administration to improve hemodynamics for adrenaline-resistant anaphylactic shock in patients taking β-blockers regularly, and the initial recommended bolus dose of glucagon is 1–2 mg intravenously." (PMID 34907487, 2021). "Surprisingly, even though multiple anaphylaxis management guidelines recommend glucagon infusions in cases of concomitant beta-blocker therapy in anaphylactic patients, it has not been administered in any of the severe or refractory cases." (PMID 31749797, 2019). "Previous research has shown that glucagon has antiarrhythmic effect during anaphylaxis and that inhibition of histamine release and vasodilatation probably play a major role in the mechanism of this antiarrhythmic activity of glucagon." (PMID 24895609, 2014). "Decrease of the BF in the presence of glucagon indicates that glucagon intensifies histamine capturing by the cells in the heart, even before anaphylaxis." (PMID 24895609, 2014). "In the second part of this study, we investigated NO and parameters of the oxidative stress during anaphylaxis in the absence and in the presence of glucagon." (PMID 24895609, 2014). "During anaphylaxis, coronary perfusion pressure was significantly increased in the absence of glucagon (32.4%; P < 0.05) while in the presence of glucagon it was increased by only 16.5% compared to the initial value before glucagon treatment." (PMID 24895609, 2014). "This means that glucagon during anaphylaxis reduced the level of endogenous histamine, which led to increase of exogenous 3H-histamine binding to its membrane receptors/transporters of the heart cells and, consequently, to an increase in 3H-histamine Umax⁡." (PMID 24895609, 2014). "The results presented in this study indicate that glucagon pretreatment increases Unet of 3H-histamine and decreases its BF, before anaphylaxis." (PMID 24895609, 2014). "Then, our results indicate that glucagon pretreatment increases Unet of 3H-histamine and decreases its backflux (BF), before anaphylaxis." (PMID 24895609, 2014). "This indicates a possible attenuation of histamine release from the mast cells during anaphylaxis in the presence of glucagon and can explain increased Umax⁡ of exogenously injected 3H-histamine in this situation." (PMID 24895609, 2014). "Our results indicate unchanged Unet, Umax⁡, and backflux during anaphylaxis (P > 0.05) in the presence of glucagon when compared to the corresponding values before anaphylaxis." (PMID 24895609, 2014). "During anaphylaxis, in the presence of glucagon, the values of 3H-histamine Umax and Unet are significantly higher and backflux is significantly lower in the presence of glucagon when compared to the corresponding values in the absence of glucagon." (PMID 24895609, 2014). "This means that the increase of coronary perfusion pressure that occurred during anaphylaxis was reduced in the presence of glucagon." (PMID 24895609, 2014).
anaphylaxis (continued). "Similarly, in a report by the Royal College of Anaesthetists of 266 patients with severe intraoperative anaphylaxis, glucagon was administered (65 min after onset) in only 1 patient (who died)." (PMID 34907487, 2021). "Therapeutic approaches to anaphylaxis such as adrenaline as first-line treatment, glucagon as second-line treatment, and anti-histamines as third-line treatment have long been attempted and developed; however, there are still unmet therapeutic needs for anaphylaxis." (PMID 34737708, 2021). "Finally, even though the mechanism(s) of the beneficial action of glucagon on cardiac anaphylaxis is still unclear, the present study extends our knowledge and clearly indicates the key involvement of histamine, NO, and free radicals during this process." (PMID 24895609, 2014). "The possible effect of glucagon on histamine release and/or on histamine uptake from the extracellular space could be relevant to cardiac anaphylaxis especially if it would decrease histamine release/downstream effects." (PMID 24895609, 2014). "Furthermore, glucagon-induced vasodilatation prevents higher increase in coronary perfusion pressure that occurs during anaphylaxis." (PMID 24895609, 2014). "Beside the higher Umax⁡ of exogenously injected 3H-histamine in the presence of glucagon, as the consequence of decreased release of endogenous histamine during anaphylaxis, it seems like glucagon has another effect reflected by the changes in Unet and especially BF of 3H-histamine." (PMID 24895609, 2014). "In the second group of experimental animals (n = 8) we investigated dynamics of 3H-histamine uptake by the heart, during a single 3H-histamine passage through the coronary circulation, before and during anaphylaxis, but, in this case, in the presence of glucagon." (PMID 24895609, 2014). "In this study we investigated the influence of acute glucagon applications on 3H-histamine uptake by the heart, before and during anaphylaxis, as well as the influence of glucagon on level of histamine, NO, and oxidative stress parameters in the venous effluent during anaphylaxis." (PMID 24895609, 2014). "Second-line medication like dopamine, glucagon, and methylene blue were not given in all refractory anaphylaxis cases as well as in severe non-refractory ones." (PMID 31749797, 2019). "In 6 cases of refractory anaphylaxis (14.3%) patients reported receiving beta-blockers as a concomitant medication, but none of these patients received a glucagon infusion." (PMID 31749797, 2019). "On the other hand there is no change in histamine concentration during glucagon perfusion before anaphylaxis compared to the period without glucagon." (PMID 24895609, 2014). "During anaphylaxis, 3H-histamine Umax⁡ was significantly higher in the presence of glucagon when compared to the corresponding value in the absence of glucagon." (PMID 24895609, 2014). "Positive inotropic effect occurring in anaphylaxis was not significantly changed in the presence of glucagon." (PMID 24895609, 2014). "Our results showed that significant increase of histamine release (P < 0.05) occurs during anaphylaxis (10.35–10.45 · 10−8 μM) in the absence of glucagon." (PMID 24895609, 2014). "At the same time, glucagon significantly decreases histamine concentration in coronary venous effluent during anaphylaxis, without affecting histamine level before it." (PMID 24895609, 2014). "Before anaphylaxis, glucagon pretreatment does not change 3H-histamine Umax and the level of endogenous histamine." (PMID 24895609, 2014). "The reason glucagon is not administered for refractory anaphylaxis could be that glucagon is not widely recognized as a treatment for anaphylaxis." (PMID 34907487, 2021). "Furthermore, in the presence of glucagon, administration of the ovalbumin (anaphylaxis) failed to increase the production of O2−." (PMID 24895609, 2014). "Then, in the presence of glucagon, O2− level fails to increase during anaphylaxis." (PMID 24895609, 2014).
anaphylaxis (continued). "However, this increase of histamine level during anaphylaxis in the presence of glucagon was significantly lower (P < 0.05) when compared to the increase of histamine release during anaphylaxis in the absence of glucagon." (PMID 24895609, 2014). "Also, during anaphylaxis, in the presence of glucagon, Umax⁡ and Unet were significantly higher and BF was significantly lower when compared to the corresponding values in the absence of glucagon." (PMID 24895609, 2014).
Anorexia (9 papers, 2015 to 2025). Lack of desire to eat (loss of appetite). "This work reveals the molecular underpinnings by which glucagon controls feeding that may lead to a better understanding of disease states linked to anorexia and cachexia." (PMID 26909312, 2015). "Hypothalamic GCG activated GCGR to stimulate downstream PKA pathway in the hypothalamic ARC, as i.c.v. co-infusion of the GCGR antagonist des-His1-[Glu9] GCG amide or the PKA inhibitor H-89 negated the ability of central GCG to induce anorexia." (PMID 28223965, 2017). "This, in turn, suggests that DIO-induced hypothalamic glucagon resistance that leads to hepatic glucose production or anorexia is mediated through different mechanisms." (PMID 26909312, 2015).
colorectal cancer (9 papers, 2018 to 2026). A primary or metastatic malignant neoplasm that affects the colon or rectum. "Past studies have understood the TMEM236 highly expressed in pancreatic α cells that secrete glucagon, elevating blood glucose, also considered to be a potential novel diagnostic biomarker for colorectal cancer, due to significantly downregulated in colorectal tumors." (PMID 41544045, 2026). "The neuroendocrine peptide glucagon (GCG) is implicated in colorectal cancer." (PMID 35340411, 2022). "The present study is aimed at investigating the regulating mechanisms of glucagon involvement in colorectal cancer." (PMID 35340411, 2022). "Previous research has shown that aberrant GCG gene expression distinguished colorectal cancer tissue from hyperplastic polyps with 100% sensitivity." (PMID 35340411, 2022). "Publicly available data from the TCGA database was utilized to explore the expression pattern and regulating role of glucagon (GCG) in colorectal cancer (COADREAD) including colon adenocarcinomas (COAD) and rectum adenocarcinomas (READ)." (PMID 35340411, 2022). "Elevated glucagon promotes release of glucose which stimulates tumor protein synthetic rate to double in colorectal cancer." (PMID 31889941, 2019). "First, the focus was on the activation of MAPK signaling mediated by glucagon, which governs the development and progression of colorectal cancer." (PMID 29535833, 2018). "As for the role of glucagon in cancer, glucagon has been shown to enhance growth of cultured human colorectal cancer cells in vitro." (PMID 29535833, 2018). "Therefore, GCG may be regarded as a potential therapeutic target for treating colorectal cancer." (PMID 35340411, 2022). "However, the role of GCG and GLP 1 and 2 in colorectal cancer is yet to be fully elucidated." (PMID 35340411, 2022).
gastrinoma (9 papers, 2014 to 2023). "In this test, glucagon is infused at 20 μg/kg/h for 30 min: Diagnosis of gastrinoma is likely when the percentage of increase over the baseline gastrin peaks within 10 min following glucagon administration, with circulating gastrin over 200 pg/mL." (PMID 31382663, 2019). "The glucagon stimulation test is another stimulation test used for the diagnosis of gastrinomas." (PMID 31382663, 2019). "Histologic preparations should be reevaluated by IHC to guide the search for the primary tumor: TTF-1 (pulmonary or medullary thyroid carcinoma), CDX-2 (intestinal), PAX-8, histidine-decarboxylase (pancreatic), xenin (duodenal), gastrin (occult gastrinoma), and PP/glucagon (pancreatic)." (PMID 25038902, 2014). "The other functioning Pan-NETs including gastrinomas and glucagonomas are also more strongly positive for SPY than CgA, suggesting active SV involvement on the early gastrin and glucagon section, respectively." (PMID 32020844, 2020).
Erythema (8 papers, 2011 to 2025). Redness of the skin, caused by hyperemia of the capillaries in the lower layers of the skin. "The most common symptoms related to glucagon are weight loss, necrolytic migratory erythema, and chronic diarrhea, which were observed and documented in one patient in our review." (PMID 40941664, 2025). "Somatostatin analogs, especially octeotride but also lantreotide, have a role in lowering the serum concentration of glucagon, help to limit the tumor and have demonstrated a real success in resolving necrolytic migratory erythema." (PMID 37628857, 2023). "The use of glucagon is generally safe, but the limited solubility in aqueous solutions, and the possibility of AEs, including necrolytic migratory erythema, need consideration." (PMID 33013678, 2020). "Another child exhibited necrolytic migratory erythema while receiving glucagon over a period of 60 days." (PMID 33013678, 2020). "The diagnosis of this pathology includes both the clinical findings, including the appearance of necrolytic migratory erythema, and the documentation of elevated serum glucagon levels but also the evidence of a glucagon-secreting tumor from the islet cells of the pancreas." (PMID 37628857, 2023). "More cases of skin and subcutaneous tissue disorders were reported for dasiglucagon relative to SoC treatment, including 2 clinically confirmed cases of necrolytic migratory erythema, a skin condition that may arise from sustained exposure to high levels of glucagon." (PMID 37930757, 2024). "Pseudoglucagonoma syndrome is defined as the presence of necrolytic migratory erythema in the absence of a glucagon-secreting tumor." (PMID 38738007, 2024).
Abdominal obesity (7 papers, 2015 to 2024). Excessive fat around the stomach and abdomen. "We also found the same outcomes and observed that glucagon was independently and positively associated with measures of central obesity in the current study." (PMID 33758717, 2021). "The present study indicated a positive association of fasting glucagon level with central obesity in type 2 diabetic subjects." (PMID 33758717, 2021). "Moreover, glucagon is associated with central obesity in type 2 diabetic patients." (PMID 33758717, 2021). "Additional studies are necessary to confirm and further clarify the clinical implications of fasting glucagon levels with glucose hemostasis and abdominal obesity." (PMID 33758717, 2021). "The glucoregulatory functions of insulin have been widely studied, whereas the association of glucagon with abdominal obesity has been sparsely researched, and no study is available in South Asians." (PMID 28634585, 2017).
enteropathy (7 papers, 2016 to 2025). "Numerous cytokines that circulate at very low concentrations were not able to be quantified in the cohort and several of these (amylin, glucagon, interferon-γ, IL-1B, IL-17A) have direct associations with MetS, which may undercut the argument for enteropathy as an etiology for MetS." (PMID 36096405, 2022).
Hypoinsulinemia (7 papers, 2001 to 2025). A decreased concentration of insulin in the blood. "It is therefore quite feasible that β cells morph into other islet cell types, perhaps α-like glucagon-producing variants, accounting for the hyperglucagonemia and hypoinsulinemia of OLETF rats." (PMID 31440379, 2019). "The underlying pathophysiology of DKA revolves around an overall state of hypoinsulinemia and heightened catabolism resulting from elevated glucagon, cortisol, catecholamines, and growth hormone levels." (PMID 39913488, 2025). "However, the late hyperglycemicphase (450 days), which was not accompaniedby hypoinsulinemia, was observed after thehyperglucagonemia (390 days) produced by abundantimmunostained A-cells giving rise to a 3-foldincrease in pancreatic glucagon stores." (PMID 12369713, 2001).
hypothyroidism (7 papers, 2022 to 2025). Abnormally low levels of thyroid hormone. "The cutoff value of serum glucagon level associated with NAFLD in patients with hypothyroidism was 85 ng/L with 90% sensitivity, 100% specificity, AUC was 0.955 and P < 0.001." (PMID 40069760, 2025). "Of interest, fasting glucagon predicts NAFLD in patients with hypothyroidism at a cutoff value 85 ng/L with 90% sensitivity, 100% specificity and p < 0.001." (PMID 40069760, 2025). "The possible association between fasting glucagon and NAFLD in patients with hypothyroidism was also evaluated." (PMID 40069760, 2025). "Fasting glucagon predicts NAFLD in patients with hypothyroidism at a cutoff value 85 ng/L with 90% sensitivity, 100% specificity and p < 0.001." (PMID 40069760, 2025). "Management includes treatment of acute hypoglycemic episodes with glucose or glucagon, long-term glucocorticoids and mineralocorticoids for adrenal insufficiency, and thyroid hormone supplements for hypothyroidism." (PMID 38957156, 2024). "Fasting glucagon concentration may play a role in the development of NAFLD in patients with hypothyroidism." (PMID 40069760, 2025). "Thus, glucagon dysregulation may be considered as one of the players of the hypothyroidism induced NAFLD." (PMID 40069760, 2025). "In patients with hypothyroidism and NAFLD, serum glucagon levels were significantly and positively correlated with age, WC, BMI, FBG, HSI, CAP and LSM." (PMID 40069760, 2025).
periodontitis (7 papers, 2015 to 2025). An acute or chronic inflammatory process that affects the tissues that surround and support the teeth. "Looking more in detail to the hormone pattern coupled with periodontitis, glucagon levels were found to be elevated and correlated with the severity of the disease." (PMID 30451975, 2019). "When comparing different stages of PD, glucagon levels were related with the severity of periodontitis (16.17 ± 9.95, 25.25 ± 4.34, 39.24 ± 4.45 ng/l from stages I to III; p = 0.03)." (PMID 30451975, 2019). "Periodontitis may contribute to HADHA suppression through insulin resistance-induced glucagon elevation or oral-gut-liver axis infection, activating lysosomal degradation pathways and impairing fatty acid oxidation." (PMID 40951429, 2025).
pheochromocytoma (7 papers, 2016 to 2023). "On the other hand, increased insulin resistance on phaeochromocytoma is caused by stimulated gluconeogenesis and glycogenolysis in the liver, which arises from an excess of glucagon and increase of free fatty acids as well as elevated glucose uptake in skeletal muscle." (PMID 33324347, 2020). "Our aim was to investigate the effects of long-term catecholamine excess on circulating glucagon-likepeptide-1 (GLP-1) levels in patients with pheochromocytoma/paraganglioma (PPGL)." (PMID 36569401, 2022). "Administration of glucagon which stimulates secretion of catecholamines by the pheochromocytoma, as happened in patient 4, has also previously been described as an eliciting factor for PPGL crisis." (PMID 33575936, 2021). "Thirty patients had tumor markers within 30 days of starting treatment and periodically while on treatment (pancreastatin, gastrin, glucagon, neurotensin; metenephrines for pheochromocytoma/paraganlgioma)." (PMID 29262620, 2017). "Considering excess of catecholamine leads to elevation of glucagon through adrenergic β2 and α1 receptors together, the results of the study about glucagon secretion might indicate there exists some unknown mechanism of glucagon secretion in patients with phaeochromocytoma." (PMID 33324347, 2020). "Furthermore, they might lead to clarification of the mechanism of increased glucagon secretion after extirpation of phaeochromocytoma, which was seen in the study by Petrák and co-workers." (PMID 33324347, 2020).